IL17A (interleukin 17A)
Diseases named in the same sentence as IL17A in open-access papers (continued):
Sharing a sentence is not in itself a finding about the gene and the disease.
liver fibrosis (continued). "However, the role of interleukin 17A (IL-17A) in liver fibrosis was examined by very few studies." (PMID 34804155, 2021). "Moreover, the absence of IL-17A signaling has been implicated in alleviating liver fibrosis in murine schistosomiasis." (PMID 32611373, 2020). "Because the neutralization of IL-17A restored autophagy activity and attenuated the hepatic fibrosis, and IL-17A inhibited autophagy by phosphorylating STAT3, we examined whether inhibiting autophagy by activating STAT3 could reverse the antifibrotic effect of IL-17A-neutralizing Ab." (PMID 28039485, 2017). "However, it is largely unknown whether increased IL-17A confers the inhibition of autophagy activity or whether regulation mediated by other molecules occurs downstream of IL-17A in the development of hepatic fibrosis." (PMID 28039485, 2017). "Our study suggests that the IL-17A/STAT3 signaling pathway plays a crucial role in the pathogenesis of hepatic fibrosis through suppressing hepatocellular autophagy and that blocking this pathway may provide therapeutic benefits for the treatment of hepatic fibrosis." (PMID 28039485, 2017). "The synergistic effects of IL-17A and TGF-β cytokines further activate HSCs, leading to increased collagen production and exacerbating liver fibrosis." (PMID 39995661, 2025). "A recent study has demonstrated that IL-17A overexpression upregulates fibroblast activation protein-α expression, a critical regulator of HSC activation, thereby promoting liver fibrosis and tumorigenesis in both in vivo and in vitro experimental models." (PMID 39148730, 2024). "Pharmacological or genetic inhibition of IL-17 production or its signaling pathway (Il17a-/- or Il17ra-/- mice, respectively) in various liver fibrosis models led to reduced HSC activation and limited liver fibrosis progression." (PMID 39156888, 2024). "Our findings underscore the role of IL-17A and its potential relationship with inflammatory markers in MASLD pathogenesis and the progression to hepatic fibrosis." (PMID 39335657, 2024). "This study investigated the possible associations between the plasma levels of inflammatory markers, IL17A/F, and TLR4 and their connections with the degree of steatosis and hepatic fibrosis among patients with MASLD." (PMID 39335657, 2024). "In this study, in vivo and in vitro experiments were performed to verify the promoting effects of IL-17a administration, IL-17a overexpression, and FAP upregulation in HSCs on liver fibrosis and liver tumorigenesis." (PMID 38740736, 2024). "In mice, the inhibition of IL-17A showed reduced mRNA levels of profibrogenic genes, such as COL1A1, and a reduced degree of liver fibrosis." (PMID 36625344, 2023). "We therefore performed immunofluorescent staining using CCR6 as marker for IL-17A–producing CD4+ T cells, and α-smooth muscle actin (αSMA) as marker for the cells potentially responsible for liver fibrosis." (PMID 36625344, 2023). "The IL-1β produced by those injured kupffer cells further promoted the IL-17A production in γδ T cells in a short time and increased IL-17A production in CD4+ T cells and liver fibrosis after chronic alcohol consumption." (PMID 36276639, 2022). "Therefore, TN could accelerate liver fibrosis in mice via IL-17A signaling pathway." (PMID 34124102, 2021). "TLR3 activation on HSCs exacerbates liver fibrosis by augmenting the production of CCL-20 and IL-17A." (PMID 34064375, 2021). "Active liver fibrosis is accompanied by IL-17A+ Th17, myeloid-derived suppressor cells (MDSCs), LTγδ, MAIT, ILC3 cells infiltration in particular in CCl4 or BDL-inducing liver fibrosis mice models." (PMID 34211477, 2021). "In CCl4-induced acute liver injury and early stage liver fibrosis, exosomes released by hepatocytes bind to TLR3 and activate HSCs to produce IL-17A, which promotes the production of IL-17A by hepatic γδ T cells to aggravate liver fibrosis." (PMID 33869241, 2021).
liver fibrosis (continued). "The neutralization of Th17 cells attenuates liver fibrosis in BDL and CCl4 models through IL-17, IL-1b, TNF-α, IL-2, IL-6, TGF-β serum levels reduction, and downregulation of IL17A and the IL6/STAT3 signaling pathway." (PMID 31671842, 2019). "In vivo studies confirmed that activation of TLR3 in HSCs by exosomes derived from damaged hepatocytes exacerbates liver fibrosis by enhancing the production of chemokine (C-C motif) ligand 20 (CCL20) and interleukin-17A (IL-17A)." (PMID 30469540, 2018). "On the other hand, IL17A signaling activates STAT3 and is suggested to promote the development of liver fibrosis." (PMID 30346985, 2018). "The plasma levels of the IL17A cytokine (Kruskal–Wallis test, p = 0.02427), IL17F cytokine (Kruskal–Wallis test, p = 0.02575), and TLR4 (Kruskal–Wallis test, p < 0.0001) were significantly different among patients with various stages of liver fibrosis." (PMID 40332363, 2025). "The IL17A-G197A GA and AA genotypes were more frequent in patients with advanced liver fibrosis compared to those without fibrosis (GA genotype frequency: 42.9% vs. 7.7%; AA genotype frequency: 14.3% vs. 5.1%; adjusted p = 0.0423)." (PMID 40332363, 2025). "Previous studies have shown that patients with CHC have increased levels of IL-17A and IL-23 in comparison with healthy group, but these studies have not included the degree of liver fibrosis in the analysis." (PMID 37569857, 2023). "Xiao Wei Zhang found that activation of the IL-17A/STAT3 pathway can inhibit autophagy in liver cells, thus aggravating liver fibrosis, while an IL-17A inhibitor could reverse the development of fibrosis." (PMID 36761734, 2023). "Further studies showed that BM-MSCs could play a protective role in liver fibrosis treatment by affecting the IL-6/STAT-3 signaling pathway and downregulating IL-17A." (PMID 35895169, 2022). "In murine schistosomiasis, the absence of IL-17A signaling has been related to reduced liver fibrosis." (PMID 35844540, 2022). "Meanwhile, IL-17A upregulates and stabilizes TGF-β receptor II (TGF-βRII) expression on the surface of HSCs through the JNK signaling pathway and enhances SMAD2/3 phosphorylation to promote liver fibrosis." (PMID 33869241, 2021). "Notably, previous studies have suggested the critical role of IL-17A and IFN-γ in the pathogenesis of hepatic fibrosis." (PMID 34124102, 2021). "An in vitro study showed that IL-17A enhances the expression of pro-fibrotic genes (e.g., ACTA2 and COL1A1) by hepatic stellate cells through JNK-dependent up-regulation of TGF-β receptor on these cells, providing a possible mechanism for liver fibrosis." (PMID 33013934, 2020). "In the present study, we evaluated the capacity of the BM-MSCs in the modulation of cytokines milieu and signal transducers, based on unique inflammatory genes Il17a and Il17f and their receptors Il17rc and their effect on the IL6/STAT3 pathway in CCl4-induced liver fibrosis in rats." (PMID 30346985, 2018). "The importance of IL-17F in chronic hepatic diseases was poorly investigated; however, we had found Th-17 associated inflammatory cytokine, IL-17F, which took a major part in severe liver fibrosis and HCC symptoms in HCV patients than other inflammatory cytokines, IL-6, and IL-17A." (PMID 28770001, 2017). "Neutralization of IL-9 further suppressed expression of inflammatory cytokines including IL-9, IL-17A, IFN-γ, TGF-β1, IL-6, IL-4 and TNF-α in the mouse model of hepatic fibrosis, suggesting IL-9 may regulate the inflammatory responses to liver fibrosis." (PMID 26728971, 2016). "An analysis of genetic data revealed that the IL17A-G197A GA and AA genotypes were more prevalent in patients with advanced liver fibrosis than in those without fibrosis (GA genotype frequency: 42.9% vs. 7.7%, AA genotype frequency: 14.3% vs. 5.1%, adjusted p = 0.0423)." (PMID 40332363, 2025).
liver fibrosis (continued). "Interleukin-17A (IL-17A [also named IL-17]), a member of the IL-17 family that has emerged as a crucial proinflammatory cytokine, is typically highly expressed in the liver after high-fat-diet (HFD) feeding and promotes the progression of NASH and liver fibrosis (2, –, 5)." (PMID 35266816, 2022). "Type 3 inflammation, characterized by a polarization towards a Th17 response and the production of IL-17A, IL-17F, IL-22 and IL-26 by Th17 cells, Th 22 cells, neutrophils and mast cells has been identified as a driver of chronical liver injury and of TGF-β-dependent liver fibrosis." (PMID 33036244, 2020). "Noticeably, one of the Stat3 signaling cytokine with pro-fibrogenic properties is IL17A, enhancing activation of hepatic myofibroblasts either directly or through IL6 secretion and collected evidences indicate the contribution of activated STAT3 in liver fibrosis." (PMID 30346985, 2018). "BM-MSCs might activate the IL6/STAT3 signaling pathway and promote cell invasion in hepatocellular carcinoma, but the immunomodulatory role of BM-MSCs on IL17A/IL6/STAT3 was not fully elucidated in liver fibrosis." (PMID 30346985, 2018). "The severity of liver fibrosis in HCV patients was associated only with IL-17F, but not with IL-17A, suggesting that IL-17F might be a better biomarker than IL-17A for HCV-associated fibrosis progression." (PMID 28770001, 2017). "In current study, we further find that IL-17A inhibits autophagy via the activation of STAT3, which may hinder the degradation of collagen and the clearance of injured tissue debris and interfere with the resolution of hepatic fibrosis." (PMID 28039485, 2017). "Although the effect of BM-MSCs on IL6/STAT3 pathway was conducted in cancer and has shown that MSCs could promote progression of cancer through activation of IL6/STAT3 pathway, the immunomodulatory role of BM-MSCs on IL17A/IL6/STAT3 was not fully elucidated in liver fibrosis." (PMID 30346985, 2018). "IL-17A levels did not increase after HFD feeding, indicating that this cytokine may be specifically involved in the induction of liver fibrosis." (PMID 37774007, 2023).
plaque psoriasis (191 papers, 2013 to 2026). "Only for plaque psoriasis patients were levels of anti-CA IgA positively associated with IL-17F and IL-17A responses, in CLA+ T cells/EPI but also in CLA− T cells/EPI cocultures." (PMID 33546306, 2021). "A meta-analysis of twenty-seven RCTs showed that IL-17A inhibitors increased the risk of AEs in moderate-to-severe plaque psoriasis." (PMID 33432451, 2021). "Vunakizumab, a novel humanized IgG1/κ monoclonal antibody that selectively targets interleukin (IL)-17A, has received approval for the treatment of moderate-to-severe plaque psoriasis in China." (PMID 41601722, 2026). "Bimekizumab (BKZ), a monoclonal antibody targeting IL-17A and IL-17F, has shown high efficacy in plaque psoriasis." (PMID 42279028, 2026). "Background and Objectives: Ixekizumab is a human monoclonal antibody targeting interleukin-17A, approved for the treatment of moderate-to-severe plaque psoriasis." (PMID 41155814, 2025). "Netakimab, a chimeric IgG1 monoclonal antibody against IL-17A, was developed in Russia and approved in 2019 for moderate-to-severe plaque psoriasis." (PMID 40303401, 2025). "Secukinumab is a fully human monoclonal antibody that selectively targets interleukin-17A (IL-17A) and is approved for the treatment of adult patients with moderate-to-severe plaque psoriasis who are candidates for systemic therapy or phototherapy." (PMID 40746559, 2025). "BKZ is a monoclonal IgG1 antibody that selectively inhibits interleukin (IL)‐17F and IL‐17A and is approved for the treatment of plaque psoriasis." (PMID 41074452, 2025). "Although IL-17C and IL-17F are found at higher concentrations in psoriatic lesions, IL-17A is considered the most biologically active cytokine of the group and a central mediator of inflammation and tissue damage in plaque psoriasis." (PMID 41155814, 2025). "Among them, secukinumab—a monoclonal antibody against IL-17A—has demonstrated significant efficacy in treating moderate-to-severe plaque psoriasis." (PMID 40746559, 2025). "There are three anti-IL-17 monoclonal antibody agents which have approved by the US Food and Drug Administration for the treatment of moderate-to-severe plaque psoriasis: secukinumab and ixekizumab (IL-17 A antagonists), and brodalumab (IL-17RA antagonist)." (PMID 40055805, 2025). "We aimed at identifying neutrophils (via Ly6G staining), accumulating in psoriatic skin of CD11c-IL-17Aind/ind mice, and Th17 cells (via RORγT staining), releasing IL-17A, both key events in the pathomechanism of human plaque psoriasis." (PMID 41341581, 2025). "In 2015, the FDA approved Secukinumab, a fully human monoclonal antibody targeting IL-17A, for adults with moderate-to-severe plaque psoriasis unsuitable for phototherapy or systemic therapy." (PMID 40303401, 2025). "Bimekizumab, a humanized monoclonal antibody, exerts its therapeutic effect by inhibiting interleukin-17A/F and is indicated for the treatment of moderate-to-severe plaque psoriasis in adult patients." (PMID 41560729, 2025). "Bimekizumab, a novel biologic immunotherapy, exerts its therapeutic effect in plaque psoriasis by selectively neutralizing IL-17A and IL-17F." (PMID 41560729, 2025). "We conducted a prospective observational study to characterize serum cytokine profiles associated with SR status in biologic-naïve patients with moderate-to-severe plaque psoriasis treated with secukinumab, an IL-17A inhibitor." (PMID 40650209, 2025). "And, targeting IL‐17A treatment has been demonstrated as an effective and guideline‐recommending therapy for moderate‐to‐severe plaque psoriasis." (PMID 39660880, 2024). "Secukinumab, an IL-17A inhibitor, has demonstrated efficacy and safety in treating moderate-to-severe plaque psoriasis (PsO)." (PMID 38999429, 2024). "The efficacy and safety results with monoclonal antibodies targeting IL‐17RA (brodalumab) and IL‐17A (ixekizumab and secukinumab) validate IL‐17 as an effective therapeutic target for the treatment of plaque psoriasis." (PMID 39355734, 2024).
plaque psoriasis (continued). "Expression levels of serum HMGB1, TLR4, IL‐23, and IL‐17A in patients with psoriasis vulgaris and healthy control, which are denoted by (x ̄ ± s) or M (P25, P75)." (PMID 38414294, 2024). "Interleukin-17A therapeutic inhibitors are among the most effective treatment methods for moderate-to-severe plaque psoriasis (PP)." (PMID 38956402, 2024). "Clinical trials have demonstrated its efficacy in reversing plaque psoriasis histopathology by curbing IL-17A production, thereby facilitating plaque resolution." (PMID 39311381, 2024). "Anti IL-17A therapies have been shown to be very effective in plaque psoriasis and the main multi-center studies, SUPREME and its post hoc analysis, have demonstrated it." (PMID 38695018, 2024). "In clinical practice, monoclonal antibodies blocking either IL‐17A or its receptor have been confirmed to be the first‐line treatment for moderate‐to‐severe plaque psoriasis (the clinical PASI score> 10)." (PMID 39660880, 2024). "Background: the present multicenter retrospective study aimed to evaluate the efficacy and safety of intra-class switching between interleukin-17A (IL-17A) inhibitors, specifically from ixekizumab to secukinumab, in patients with plaque psoriasis." (PMID 39728081, 2024). "Serum levels of HMGB1, TLR4, IL‐23, and IL‐17A were quantified in 50 patients with moderate‐to‐severe plaque psoriasis and 30 healthy controls." (PMID 38414294, 2024). "Secukinumab, an interleukin-17A inhibitor (IL-17A), represents a newer class of biological medications approved by the Food and Drug Administration in 2015 for the treatment of plaque psoriasis and axial spondyloarthritis." (PMID 38523953, 2024). "Herein, we report a case of pustular psoriasis in a 65 year-old male with plaque psoriasis after treatment with an IL-17A inhibitor." (PMID 38695018, 2024). "From the group of IL-17 inhibitors, Ixekizumab was the first IL-17A antagonist approved in 2020 for the treatment of pediatric patients with moderate to severe plaque psoriasis." (PMID 39518448, 2024). "In conclusion, this is the first reported case in China of a patient with plaque psoriasis developing symptoms of pustular psoriasis after treatment with the IL-17A antagonist secukinumab." (PMID 38695018, 2024). "Bimekizumab was the first IL-17A/IL-17F dual-target inhibitor for moderate-to-severe plaque psoriasis." (PMID 37920459, 2023). "In a 28-year-old female patient with extensive cutaneous LP, we took advantage of the availability of Secukinumab, an anti-IL-17A monoclonal antibody which is approved for the treatment of psoriasis vulgaris." (PMID 37415985, 2023). "Similar to risankizumab, these common AEs were observed in plaque psoriasis patients assigned to active treatment arms in clinical trials of other IL-23 inhibitors, IL-17A inhibitors, and TNF inhibitors." (PMID 37256136, 2023). "In summary, our pre-clinical study showed that inhibition of the IL-36 signaling pathway constitutes an attractive approach for the treatment of IL-17A-driven psoriasis vulgaris." (PMID 38162658, 2023). "Inactivated SARS‐CoV‐2 vaccines do not have significant impacts on the safety and efficacy of biologics (TNF‐α inhibitors or IL‐17A inhibitors) in patients with moderate to severe plaque psoriasis." (PMID 37506146, 2023). "To clarify, if inhibition of IL-36 signaling can block IL-17A-driven plaque psoriasis, especially when inflammation has already been induced, we investigated the effects of systemic anti-IL36R antibody application in two different mouse models." (PMID 38162658, 2023). "Secukinumab, a human IgG1 monoclonal antibody which was approved in 2015 for the treatment of plaque psoriasis by targeting IL-17A, and has demonstrated greater efficacy than ustekinumab." (PMID 37029373, 2023). "Biologics inhibiting these pathways show great efficacies in treating plaque psoriasis, especially when blocking interleukin-17A." (PMID 35669784, 2022).